NGF (nerve growth factor)
Diseases named in the same sentence as NGF in open-access papers (continued):
Sharing a sentence is not in itself a finding about the gene and the disease.
Sepsis (10 papers, 2008 to 2026). Sepsis is defined as life-threatening organ dysfunction caused by a dysregulated host response to infection. "Although there is clinical evidence associating NGF with sepsis, further research is required to clarify its precise mechanism." (PMID 38313013, 2024). "Activation of the NGF signaling pathway in elderly patients with sepsis was associated with a poor prognosis in one clinical study." (PMID 38313013, 2024). "In microbial infections such as sepsis, NGF and BDNF have been implicated in both protective and deleterious functions." (PMID 39596862, 2024). "For example, sepsis can lead to the loss of noradrenergic (sympathetic) nerves inside the human spleen possibly because of altered immune responses (e.g., increased inflammatory cytokines, immunosuppression, or reduction of nerve growth factor (NGF) from immune cells)." (PMID 37767094, 2023). "Recent studies have found significantly higher concentrations of NGF in the blood of patients with sepsis than in the healthy population." (PMID 38313013, 2024). "The results showed that beta-nerve growth factor increased the risk of sepsis, while RANTES and fibroblast growth factor decreased the risk of sepsis." (PMID 38313013, 2024). "This study found that beta-nerve growth factor, RANTES, and fibroblast growth factor are associated with the risk of sepsis, with beta-nerve growth factor increasing sepsis risk and RANTES and fibroblast growth factor decreasing sepsis risk." (PMID 38313013, 2024). "The primary MR analysis by random effects IVW showed a significant causal effect of beta-nerve growth factor, RANTES, and fibroblast growth factor on the risk of sepsis." (PMID 38313013, 2024). "In animal experiments, NGF levels were significantly higher in septic rats compared to the control group 24 h after inducing sepsis with LPS (lipopolysaccharide)." (PMID 38313013, 2024). "Following anti-NGF treatment 24 h after sepsis induction, Bcl-2 expression increased, and Bax expression decreased in mouse tissue, resulting in a reduction of apoptosis." (PMID 38313013, 2024). "The findings of this study demonstrate that beta-nerve growth factor, RANTES, and fibroblast growth factor contribute to sepsis risk." (PMID 38313013, 2024). "Since T and B cell abundance in the spleen is reduced substantially during sepsis due to apoptosis, it is reasonable to conclude that the supply of NGF to support sympathetic innervation would likewise be reduced." (PMID 29270174, 2017). "Sepsis alone was also associated with reduced levels of these neurotrophins, although the magnitude of the effect varied depending on the specific neurotrophin and brain region, with greater reductions observed for BDNF and NGF." (PMID 42176200, 2026). "Additionally, we identified beta-nerve growth factor as a protective factor, and TRAIL as a risk factor for sepsis." (PMID 40797460, 2025). "Indeed, potentiated NGF levels have been shown in sepsis, where it seems to endorse the survival of nerve and immune cells." (PMID 39596862, 2024). "Additionally, MR analysis positive causal association of between beta-nerve growth factor (β-NGF) and sepsis (OR = 1.120, 95% CI: 1.037-1.211, P = 0.004)." (PMID 37915587, 2023). "Genetically predicted beta-nerve growth factor (OR = 1.12, 95% CI [1.037–1.211], P = 0.004) increased the risk of sepsis, while RANTES (OR = 0.92, 95% CI [0.849–0.997], P = 0.041) and fibroblast growth factor (OR = 0.869, 95% CI [0.766–0.986], P = 0.029) reduced the risk of sepsis." (PMID 38313013, 2024). "The results showed that beta-nerve growth factor (OR = 1.12, 95% CI [1.037–1.211], P = 0.004) increased the risk of sepsis, while RANTES (OR = 0.92, 95% CI [0.849–0.997], P = 0.041) and fibroblast growth factor (OR = 0.869, 95% CI [0.766–0.986], P = 0.029) reduced the risk of sepsis." (PMID 38313013, 2024). "This suggests that NGF may promote the progression of sepsis by inducing apoptosis." (PMID 38313013, 2024).
Sepsis (continued). "Based on the data shown here, it is our opinion that defects in mitochondrial function/oxidative phosphorylation, TGF-β, Wnt/β-catenin, nerve growth factor (NGF) and calcium signaling may play a major role in the clinical features of sepsis in elderly patients." (PMID 26047321, 2015). "Beta-nerve growth factor levels (β-NGF) (OR = 0.769, 95%CI = 0.599 ~ 0.987, P = 0.039) significantly decreased the incidence of sepsis." (PMID 39176264, 2024). "Nerve growth factor was detected in the present study, but its gene expression appeared not to be affected by LPS treatment, implying nerve growth factor may not be involved in causing astrocyte death in sepsis at the gene expression level." (PMID 19087328, 2008). "Regarding neurotrophic factors, CMS reduced the levels of BDNF, NT-3, NT-4, and NGF in both the hippocampus and frontal cortex, regardless of prior sepsis exposure." (PMID 42176200, 2026). "The role of NGF has never been investigated in sepsis, but might be involved because neuropeptides possess a broad number of regulatory functions in immunity and NGF directly affects the survival and differentiation of stem cells, granulocytes, lymphocytes and monocytes." (PMID 26047321, 2015).
amyloid (9 papers, 2014 to 2026). "The role of NGF as a therapeutic tool for AD has received a lot of attention in the last years, with strong consideration of the impairment of NGF pathway as cause of AD via the accumulation of amyloid plaques." (PMID 28670271, 2017). "AD and amyloidosis are known to impair neuronal function and affect brain neurotrophic factors (NGF and BDNF) expression." (PMID 41665021, 2026). "Further, it was suggested that there is a link between such NGF dysmetabolism and CNS inflammation in the amyloid pathology since injection of Aβ oligomers in the hippocampus of naïve rats provoked both brain inflammation and NGF dysregulation." (PMID 34434101, 2021). "An increase of NGF in the hippocampus during amyloid-induced neurodegeneration can also be considered as a case of long-term neuronal plasticity, when the survival of neurons is achieved via the mobilization of the brain stem cell reserves." (PMID 34209299, 2021). "The NGF concentration has been found to be elevated after amyloid 25–35 injection in the hippocampus and dropped down in the cerebral cortex and hypothalamus." (PMID 34209299, 2021). "Indeed, the NGF metabolic pathway has been demonstrated to be impaired in AD and other amyloid pathologies, and pharmacological manipulation of NGF metabolism has consequences in vivo for both levels of proNGF/NGF and the phenotype of BF cholinergic neurons." (PMID 30809111, 2019). "In conclusion, EGCG treatment activated the TrkA signaling, inhibited the p75NTR signaling, and adjusted the TrkA/p75NTR imbalance by increasing the NGF relative expression in APP/PS1 mice to ameliorate the behavioral deficits and amyloidosis." (PMID 24356899, 2014).
atherosclerosis (9 papers, 2010 to 2025). A disease characterized by the build-up of fatty material and calcium deposition in the arterial wall resulting in partial or complete occlusion of the arterial lumen. "Taken together, the fact that plasma NGF level is reduced in chronic as well as in acute stages of human coronary atherosclerosis, suggests the role of NT deficiency in the pathophysiology of atherosclerosis and the association of NGF with CV diseases." (PMID 30767081, 2019). "Recent human studies have reported that NGF has importance in atherosclerosis and related disorders." (PMID 30767081, 2019). "Nerve growth factor (NGF) is a potent angiogenic factor that is decreased in atherosclerosis-lesioned arteries." (PMID 26006236, 2015). "We have analyzed the statin induced miRNAs which targeted the certain pathways, including the hemostasis, RhoGTPase and pathway in NGF rear reported in the atherosclerosis." (PMID 25889164, 2015). "On the other hand, the NGF signaling pathway and opioid pathway in our study are relatively new signaling pathways in atherosclerosis." (PMID 25889164, 2015). "Mouse-specific atherosclerosis mechanisms identified in the aorta include signaling by insulin receptor, EGFR, ERBB2, NGF, and TGF-beta signaling, axon guidance, VEGF and VEGFR pathways, and Tap63 and DeltaNp63 pathways." (PMID 38060277, 2023). "One of the possible ways for explaining the role of NGF in metabolic disorders is the fact that NGF upregulates the expression of LDL receptor-related protein, which leads to a decreased level of LDL, and subsequently a lower probability of atherosclerosis." (PMID 30767081, 2019). "The reasons remain unclear, but recent studies have reported the potential importance of neurotrophins, such as nerve growth factor (NGF) and brain-derived neurotrophic factor (BDNF), in atherosclerosis and related disorders." (PMID 20181009, 2010).
cerebral infarction (9 papers, 2011 to 2024). An ischemic condition of the brain, producing a persistent focal neurological deficit in the area of distribution of the cerebral arteries. "In a study by Pan Jiang, electroacupuncture at the governor vessel was found to enhance the expression of NGF in the cerebral infarction area, leading to a reduction in the volume of cerebral infarction and resisting nerve damage." (PMID 38625960, 2024). "According to Li, Li64, NGF increases angiogenesis in the rat brain following cerebral infarction by enhancing the in vitro and in vivo capillary-like tube development in microvascular endothelial cells." (PMID 35654991, 2022). "Conversely, glucocorticoids have also been shown to attenuate microglia/macrophage activation, reduce edema and brain infarct and contribute to injury-induced increases in NGF following TBI." (PMID 32670020, 2020). "Because DWI was sensitive to brain tissue ischemia, and made it possible to become early imaging evaluation means for NGF and other neuroprotective agents in the treatment of cerebral infarction." (PMID 29423079, 2018). "The situation of focus recovery was observed and evaluated after cerebral infarction treated by NGF and other neuroprotective agents, which needed more reliable objective indicators." (PMID 29423079, 2018). "The expression of NGF significantly increases at 6 h post-ischaemia and then quickly returns to normal levels over 12 h to 7 days in rats with cerebral infarction." (PMID 20726846, 2011). "Nerve growth factor (NGF) is a protein primarily responsible for the differentiation and survival of neurons in the peripheral nervous system, so NGF has been one of neuroprotective agents for treating cerebral infarction and ischemic brain." (PMID 29423079, 2018). "The therapeutic evaluation of NGF effect could be determine by canine cerebral infarction treated by NGF within 6 hours according to DWI and PWI." (PMID 29423079, 2018). "The magnetic resonance imaging (MRI) technology was used to study effects of NGF on cerebral infarction, and the results of MRI indexes (such as diffusion-weighted imaging (DWI) and perfusion-weighted imaging (PWI)) were compared with the results of pathology, cell biology and molecular biology." (PMID 29423079, 2018).
fibromyalgia (9 papers, 2019 to 2024). A chronic disorder of unknown etiology characterized by pain, stiffness, and tenderness in the muscles of neck, shoulders, back, hips, arms, and legs. "Given that the extant literature broadly implicates BDNF as a biomarker in fibromyalgia, and further hypothesises NGF to be implicated in the peripheral pathophysiology of fibromyalgia, our null findings will adjust how clear the current study consensus appears." (PMID 31541132, 2019). "The upregulation of brain-derived neurotrophic factor mediated by NGF participates in the pathophysiological processes, leading to long-term neuroplastic changes in persistent chronic pains, e.g., fibromyalgia." (PMID 37065490, 2023). "The potential relationship between IIS and elevated levels of NGF in fibromyalgia patients will also be covered in the subthreshold endplate potential section to follow." (PMID 35295453, 2021). "During resistance exercise, the level of circulating NGF was shown to significantly increase in patients with fibromyalgia." (PMID 33233633, 2020). "In a recent study, the level of circulating NGF was significantly decreased in fibromyalgia compared with healthy controls." (PMID 33233633, 2020). "Plasma BDNF and NGF were measured in 89 fibromyalgia patients and 36 pain-free controls, and compared using ANCOVA controlling for potential confounders, as well as Bayesian methods for parameter estimation and model evaluation." (PMID 31541132, 2019). "This is the first study to show that peripheral NGF is unperturbed in fibromyalgia patients, and further sheds doubt upon previous findings that plasma BDNF is increased in fibromyalgia." (PMID 31541132, 2019). "This cross-sectional study set out to assess and compare brain-derived neurotrophic factor (BDNF) and nerve growth factor (NGF) in plasma samples from fibromyalgia patients and healthy controls." (PMID 31541132, 2019). "This may have clinical significance as elevated levels of NGF have been identified in the CSF of fibromyalgia patients." (PMID 35295453, 2021). "We hypothesized increased levels of BDNF and NGF in fibromyalgia patients as compared to pain-free controls, indicative of peripheral sensitization in the chronic pain population." (PMID 31541132, 2019). "For the present study we investigated plasma levels of NGF, as well as BDNF as a replication attempt in a large sample of fibromyalgia patients." (PMID 31541132, 2019). "Research demonstrates biochemical and neurobiological elements of fibromyalgia which include: neurotransmitters, hypothalamic pituitary adrenal axis (HPA axis), inflammatory cytokines, monoaminergic pathways, opioid peptides, sex hormones, nerve growth factor (NGF) and local free radical insult." (PMID 33802768, 2021). "The most marked study limitation is that no cerebrospinal fluid measures of BDNF and NGF were taken, and thus no conclusions can be drawn as to whether central growth factor levels are altered in fibromyalgia." (PMID 31541132, 2019). "Contrary to the study hypotheses, fibromyalgia patients were indistinguishable from pain-free controls on both plasma NGF and BDNF levels." (PMID 31541132, 2019).
Huntington disease (9 papers, 2011 to 2025). Huntington disease (HD) is a rare neurodegenerative disorder of the central nervous system characterized by unwanted choreatic movements, behavioral and psychiatric disturbances and dementia. "In patients with Huntington's Disease, intra-striatal NGF administration is neurotrophic solely for cholinergic neurons, while transport facilitated by genetically engineered cells has shown improvements in both cholinergic and GABAergic networks." (PMID 40153582, 2024). "Other neurological disorders have been studied concerning NGF activity, such as Huntington’s disease, in which a progressive decrease of hippocampal NGF levels has been observed in different rat model ages." (PMID 35628626, 2022).
irritable bowel syndrome (9 papers, 2019 to 2025). Irritable bowel syndrome (IBS) is a chronic functional condition of the lower gastrointestinal (GI) tract characterized by abdominal pain or discomfort and disordered bowel habit (diarrhea, constipation, or fluctuation between the two). "Elevated levels of SP and NGF are strongly associated with the severity of abdominal pain symptoms, particularly in visceral hypersensitivity disorders such as irritable bowel syndrome (IBS)." (PMID 40225339, 2025). "The expression of NGF in the intestinal mucosa of irritable bowel syndrome (IBS) patients is increased, and the phenotype of EGCs is changed." (PMID 31856738, 2019).
Neurogenic bladder (9 papers, 2012 to 2023). A type of bladder dysfunction caused by neurologic damage. "Because of findings like this, contemporary treatments for neurogenic bladder have been aimed at altering conduction through afferent C fibers and the concentration of NGF in the spinal cord." (PMID 27006855, 2016). "The neurotrophin NGF plays a dynamic role in the bladder of patients with SCI, supposedly modulating neuronal cell function linked with micturition and also development of neurogenic bladder at the spinal level." (PMID 30653511, 2019). "The authors concluded that NGF had a significant synergistic effect on the development, differentiation, and functional restoration of BAM when administered with VEGF in neurogenic bladder." (PMID 35742803, 2022). "Patients with idiopathic detrusor overactivity, neurogenic bladder or inflammatory bladder diseases such as BPS/IC have been reported to have increased bladder sensation and urinary NGF levels." (PMID 27462520, 2016). "Studies conducted from the perspectives of nerves and bladder found that electroacupuncture can effectively promote the expression of nerve growth factor (NGF) and its tyrosine kinase receptor A (TrkA) in the injured spinal cord tissue of neurogenic bladder model rats." (PMID 34087850, 2021).
neuropathic pain (9 papers, 2015 to 2025). Chronic pain caused by damage to nerve fibers. "Specifically, the study found that the standardized NGF concentration was associated with nociceptive pain, including continuous, intermittent pain, and neuropathic pain, and the standardized S100A8/A9 concentration was associated with present pain intensity and continuous pain." (PMID 27936243, 2016). "Interestingly, anti-NGF treatment, in addition to reversing thermal hyperalgesia after chronic constriction injury to the sciatic nerve, can also block collateral axonal sprouting, a hallmark of neuropathic pain." (PMID 41301953, 2025). "For instance, some studies have demonstrated that intrathecal administration of NGF can alleviate hyperalgesia in neuropathic pain models." (PMID 41245866, 2025). "Among various factors involved in the pain mechanism, nerve growth factor (NGF) is known to be a pain mediator, which transmits peripheral pain signals to the brain in addition to modulating inflammatory and neuropathic pain conditions." (PMID 34203430, 2021). "As an example, these mechanisms may play a substantial role for the contrasting accommodation of pain upon prolonged electrical stimulation between healthy subjects and neuropathic pain patients, or the sensitization of nociceptors after nerve growth factor (NGF) treatment." (PMID 36926107, 2022). "Additionally, vinpocetine has direct neuronal effects that could also reduce the nociceptive inputs, including blocking the retrograde axoplasmic transport of nerve growth factor, which is proposed as its analgesic mechanism of action in neuropathic pain." (PMID 25822523, 2015). "Neurotrophic growth factors, such as nerve growth factor (NGF), are key players in driving peripheral nerve sprouting and nociceptive signal transduction in both inflammatory and neuropathic pain." (PMID 33535595, 2021). "And l-CDL induced inhibition of p-TAK1, p-MAPK, NF-kB and proinflammatory cytokines were all could be reversed by NGF, indicating that l-CDL inhibited the upregulated NGF in CCI rats and downstream TAK1-MAPK/NF-κB signaling to alleviate CCI-induced neuropathic pain." (PMID 32312253, 2020).